IL1A (interleukin 1 alpha)
Diseases named in the same sentence as IL1A in open-access papers (continued):
Sharing a sentence is not in itself a finding about the gene and the disease.
homocystinuria (1 paper, 2021). An autosomal recessive inherited metabolic disorder caused by mutations in the CBS, MTHFR, MTR, and MTRR genes. "Proinflammatory cytokines other than IL-6, namely IL-1α, IL-1β and TNF-α, are increased in a mouse model of homocystinuria and a range proinflammatory cytokines and chemokines [IL-1α, IL-6, TNF-α, IL-17, IL-12 (p70), MIP-1α and MIP-1β] are also elevated in homocystinuria patients." (PMID 34251022, 2021).
hyperandrogenism (1 paper, 2023). Excessive secretion of androgens from the adrenal glands or gonads. "The researchers found that the women with PCOS had a mean IL-1α blood concentration of 401.40 pg/ml, whereas the control group had a mean of 19.32 pg/ml only, concluding that hyperandrogenism is positively correlated with increased production of IL-1α, which in turn inhibits estradiol secretion." (PMID 37062827, 2023).
Hyperinsulinemia (1 paper, 2015). An increased concentration of insulin in the blood. "Of note, while it cannot be excluded that the association of plasma apoB with hyperinsulinemia and IR may also be related to increased production of IL-1α, which promotes IL-1Ra secretion, IL-1α is rarely found in circulation and its role in T2D in humans is less clear." (PMID 26417659, 2015).
hyperreactivity (1 paper, 2018). "Here, we demonstrate the release of the alarmin IL-1α after ozone exposure and that the acute respiratory barrier injury and inflammation and airway hyperreactivity are IL-1α-dependent." (PMID 29867931, 2018).
immune thrombocytopenia (1 paper, 2025). "This study confirms the potential relationship between circulating inflammatory proteins and immune thrombocytopenia (ITP), with four proteins (CCL4, CXCL9, IL-12B, and SCF) showing a positive association with ITP, while two proteins (IL-1α and TRANCE) exhibited a negative correlation." (PMID 40261473, 2025).
intestinal cancer (1 paper, 2024). "Previously, in a mouse model of intestinal cancer, sunitinib administration at a dosing protocol of 30 mg/kg every other day for 9 weeks resulted in a reduction in various inflammation-related factors, such as IL-6, IL-1α/1β, TNFα, and IFN-γ at the mRNA level within the GI tract." (PMID 38339116, 2024).
intracranial hypertension (1 paper, 2022). A finding characterized by increased cerebrospinal fluid pressure within the skull. "Another group of experiments on animal models of intracranial hypertension showed that increased ICP was significantly associated with increased levels of cytokines, such as IL-6, IL-18, IL-1α and IL-1β." (PMID 36441671, 2022).
invasive breast carcinoma (1 paper, 2016). A carcinoma that infiltrates the breast parenchyma. "The presence of IL-1β and IL-1α in tumor cells in patients with invasive breast cancer has also been described." (PMID 27391324, 2016).
invasive candidiasis (1 paper, 2012). "Of the cytokines induced, IL-1α, IL-1β, IL-6, IL-10, IL-17A, IL-18, IFN-γ, and TNF-α have been previously shown to play an important role in the pathogenesis of invasive candidiasis in vivo." (PMID 22916017, 2012).
irritable bowel syndrome (1 paper, 2021). Irritable bowel syndrome (IBS) is a chronic functional condition of the lower gastrointestinal (GI) tract characterized by abdominal pain or discomfort and disordered bowel habit (diarrhea, constipation, or fluctuation between the two). "Overexpressed miR-181c-5p inhibits the inflammatory response in rats with irritable bowel syndrome by silencing IL1A." (PMID 33952191, 2021).
ischemic disease (1 paper, 2019). Lack of blood supply to an area of the body, resulting in impairment of tissue oxygenation. "During ischemic disease, such as MI or cerebral infarction, or tissue injury, cell death by necrosis takes place and the IL-1α precursor is released in sterile inflammation." (PMID 31182982, 2019).
kidney cancer (1 paper, 2017). Primary or metastatic malignant neoplasm involving the kidney. "Here, we found that, in HEK293 kidney cancer cells, TGR5-transfected cells with the ligand treatment suppressed gene expression of IL-1α, IL-1β, IP-10, and MCP-1 induced by TNF-α or p65 overexpression." (PMID 28903349, 2017).
knee osteoarthritis (1 paper, 2010). "Controlling for the effects of diet and percentage body fat with a multivariate model revealed a significant association between knee osteoarthritis severity and serum levels of leptin, adiponectin, and IL-1α." (PMID 20604941, 2010). "Of these changes, systemic leptin, adiponectin, and IL-1α levels remain significantly associated with knee osteoarthritis severity when statistically controlling for the effects of diet and adiposity." (PMID 20604941, 2010). "The serum IL-1α concentration, however, was negatively associated with knee osteoarthritis score in both a bivariate and a multivariate analysis." (PMID 20604941, 2010). "Despite minimal effects of a high-fat diet on proinflammatory cytokine levels, statistically controlling for the effect of diet and percentage body fat revealed that systemic concentrations of leptin, adiponectin, and IL-1α are predictive of knee osteoarthritis severity." (PMID 20604941, 2010).
Latent infections (1 paper, 2019). "In normal to latent infections, we identified eight genes, of which three genes (FZD2, NDUFS8, NLRC4) were up-regulated, and another five genes (CCL4, IL1B, IL1A, TNF, AREG) were down-regulated." (PMID 31749827, 2019).
lateral epicondylitis (1 paper, 2012). inflammation of the lateral epicondyle. "Furthermore our results revealed that CGRP and IL-1α had significant positive correlation, and this supports that neurogenic inflammation might play a role in the pathogenesis of lateral epicondylitis." (PMID 23107345, 2012).
Legionella infection (1 paper, 2025). "We observed that monocytes cultured in aa− media had reduced IL1A and IL1B expression after treatment with GM-CSF and Legionella infection." (PMID 40470942, 2025).
leprosy (1 paper, 2015). Leprosy is a chronic infectious disease affecting primarily the skin and peripheral nervous system. "We investigated the possible effects of CYP19A1 [rs11575899], NFKβ1 [rs28362491], IL1α [rs3783553], CASP8 [rs3834129], UGT1A1 [rs8175347], PAR1 [rs11267092], CYP2E1 [INDEL 96pb] and IL4 [rs79071878] genes in a group of 141 leprosy patients and 180 healthy individuals." (PMID 26367014, 2015).
leukocytosis (1 paper, 2013). "WBC counts are elevated in ATC in part because some ATC cells produce several growth factors and cytokines, such as colony-stimulating factor (CSF), interleukin-1α (IL-1α), IL-3, and IL-6, which lead to leukocytosis." (PMID 24224029, 2013).
Listeria monocytogenes infection (1 paper, 2019). "The NAT AS-IL1α regulates IL-1α transcription and is expressed at low levels in resting macrophages and is induced by Listeria monocytogenes infection or TLR ligands followed by NF-κB activation." (PMID 30781588, 2019).
lumbar disc herniation (1 paper, 2014). "The analysis of clinical outcome over time, i.e. from inclusion to 12 months, revealed that the progression of pain and disability after lumbar disc herniation may be associated with the IL1A/IL1RN genotype." (PMID 25207923, 2014). "The combination of IL1A rs1800587 T allele and IL1RN rs2234677 A allele may increase the risk of a chronic outcome and persistent pain following lumbar disc herniation." (PMID 25207923, 2014).
magnesium deficiency (1 paper, 2023). A nutritional condition produced by a deficiency of magnesium in the diet, characterized by anorexia, nausea, vomiting, lethargy, and weakness. "The central role in mediating the inflammatory response induced by magnesium deficiency is assigned to IL-1α, which produces chemokines and adhesion molecules by activating NFkB." (PMID 36837480, 2023).
malignant mesothelioma (1 paper, 2023). A malignant neoplasm of the pleura or peritoneum, arising from mesothelial cells. "In contrast, in the malignant mesothelioma cell line panel, CCL2 expression was downregulated compared to the marked increase in CXCR2-dependent chemokines, IL-1α, and VEGF-A underscoring the critical role played by cell type in the context of arginine deprivation therapy." (PMID 37010783, 2023).
meningococcal meningitis (1 paper, 2025). "In meningococcal meningitis, antibodies targeting IFN-γ (10%), IL-1α (7%), and IL-17F (7%) were associated with infection, while antibodies against IFN-γ were more prevalent in viral meningoencephalitis (12%)." (PMID 41161094, 2025). "Patients with meningococcal meningitis had a higher prevalence of anti-IFN-γ (9 of 86 [10%] vs. 3 of 264 [1%], p = 0.004), anti-IL-1α (6 of 86 [7%] vs. 1 of 264 [0%], p = 0.015), and anti-IL-17F (6 of 86 [7%] vs. 1 of 264 [0%], p = 0.015) compared to controls." (PMID 41161094, 2025).
microcephaly (1 paper, 2021). A congenital or acquired developmental disorder in which the circumference of the head is smaller than normal for the person's age and sex. "When only cases without microcephaly were compared with controls, IL-1α and IP10 (CXCL10) were significantly higher among controls." (PMID 33875756, 2021). "When cases (with or without microcephaly) were compared with controls, IL-1α, IL-7, IP10 (CXCL10), and GCSF were significantly higher among controls." (PMID 33875756, 2021).
Middle ear cholesteatoma (1 paper, 2020). "Middle ear cholesteatoma stem cells (ME-CSCs) showed a significantly increased expression of TLR4 accompanied by a significantly enhanced LPS-dependent pro-inflammatory gene expression pattern of TNFα, IL-1α, IL-1ß, IL-6, and IL-8 compared to non-pathogenic control cells." (PMID 31947538, 2020).
middle ear inflammation (1 paper, 2020). "Inflammatory cytokines such as IL1α, IL1β, and tumor necrosis factor produced by macrophages and monocytes in response to microbial toxin play a vital role in middle ear inflammation and OM." (PMID 32391052, 2020).
muscular dystrophies (1 paper, 2021). "In muscular dystrophy, chronic inflammation is driven by pro-inflammatory cytokines such as TNFα, IL1α, and IL1β." (PMID 34439837, 2021). "The IL1α and IL1β signaling pathway should be further investigated in muscular dystrophies models." (PMID 34439837, 2021).
myoma (1 paper, 2012). "The myoma model also enabled us to show high expressions of cytokines, such as IL-1a, IL-1R1, IL-8, and NF-κB, which are all known to have reciprocal interactions." (PMID 23342263, 2012). "The cytokines IL-1a and IL-8 usually exhibited diffuse and strong expression in the HSC-3 cells (partly also exhibiting a nuclear location) in the myoma assays." (PMID 23342263, 2012).
nephritis (1 paper, 2006). Inflammation of renal tissue. "Relationship between RANTES, IL-8, MCP-1 and IL-1α polymorphisms and the presence of nephritis in SLE Spanish patients." (PMID 16719905, 2006).
nephrotic syndrome (1 paper, 2024). A collection of symptoms that include severe edema, proteinuria, and hypoalbuminemia; it is indicative of renal dysfunction. "Nephrotic syndrome is consistently associated with elevated levels of serum IL-2, IL-2R, IFN-γ, and TNF-α and normal levels of IL-1α, IL-1β, and IFN-α." (PMID 38127456, 2024).
nevus (1 paper, 2020). Nevus (or naevus, plural nevi or naevi, from nævus, Latin for "birthmark") is the medical term for sharply circumscribed[1] and chronic lesions of the skin or mucosa. "Likewise, of Il1 family members, only Il1a transcripts were detected in nevus melanocytes and they were at levels lower than in many other skin cell types." (PMID 33047672, 2020).
nicotine dependence (1 paper, 2018). Physical and psychological dependence on nicotine. "Tests for between-subject effects showed that diagnosis had significant effects on sIL-6R, sTNF-R2, and TBARS levels; age on sTNF-R1 (positive association) and sTNF-R2 (negative association); and nicotine dependence on IL-1α and sIL-2R levels." (PMID 29103192, 2018).
oral diseases (1 paper, 2021). "Since both IL-1α and IL-1β are implicated in the pathology of OM, and IL-1α at least partially regulates neutrophils in other oral diseases, we asked if blocking IL-1R in WT and Il17ra−/− mice would account for the increased damage when IL-17RA is lacking." (PMID 34220843, 2021).
osteonecrosis (1 paper, 2017). A none disease characterized by death of bone tissue due to a lack of blood supply. "IL-6- or IL-1α/β-deficient mice were also significantly resistant to osteonecrosis development in this model." (PMID 28387378, 2017). "In fact, we demonstrate that TNFα-, IL-1α/β- or IL-6-deficient mice as well as wild-type mice administered a TNFα-inhibitor were significantly resistant to development of osteonecrosis accompanying infectious myelitis, even under bisphosphonate treatment." (PMID 28387378, 2017). "Instead, we show that osteonecrosis development in infectious osteomyelitis mice administered alendronate was significantly blocked by gene targeting of either TNFα-, IL-6 or IL-1α/β, or by treatment with a TNFα inhibitor." (PMID 28387378, 2017).
ovarian adenocarcinoma (1 paper, 2005). An adenocarcinoma that arises from the ovary. "Here we directly compared the levels of gene expression of COX-2, 11βHSD-1 and -2 in response to treatment with IL-1α in normal HOSE cells and a series of cell lines derived from the ovaries of patients with ovarian adenocarcinoma." (PMID 15870720, 2005).
ovarian endometrioid cancer (1 paper, 2010). "Our present study didn't show a significant difference expression of IL-1α cell-associated expression between ovarian endometrioid cancer cells (TOV-112D) and endometrial cells with high expression in clear cell cells (TOV-21G)." (PMID 20181040, 2010).
penile squamous cell carcinoma (1 paper, 2025). "Immunohistochemistry (IHC) analysis of eight cytokines (IL-1A, IL-1B, IL-2, IL-6, IL-12, TGF-β1, TNF-α and IFN-γ) was performed in paired tumour tissues and corresponding negative surgical margins from 94 patients with penile squamous cell carcinoma." (PMID 41465261, 2025).
penile tumour (1 paper, 2025). "Transcriptomic analyses have demonstrated the elevated mRNA expression of IL-1A, IL-1B, IL-6, IFN-γ, and TGF-β1 in penile tumour tissue, with a positive correlation between IFN-γ levels and tumour stage." (PMID 41465261, 2025).
periapical granuloma (1 paper, 2018). Chronic nonsuppurative inflammation of periapical tissue resulting from irritation following pulp disease or endodontic treatment. "We found that IL-1α and IL-1β expression levels were both associated with the inflammation grade in periapical granulomas (P < 0.05)." (PMID 30012121, 2018). "The relationships between the IL-1α and IL-1β protein expression levels and the inflammation grade in periapical granulomas from primary teeth were analysed by Spearman’s rank correlation." (PMID 30012121, 2018). "ELISA results showed that IL-1α and IL-1β levels were higher in the periapical granuloma group than in the radicular cyst and normal control groups (P < 0.05)." (PMID 30012121, 2018). "Immunohistochemistry results showed that both IL-1α and IL-1β were expressed in periapical granulomas and cysts." (PMID 30012121, 2018). "Our data support that IL-1α in periapical granulomas from primary teeth was positively correlated with IL-1β." (PMID 30012121, 2018). "It seems that a synergic effect of IL-1α and IL-1β exists in the progression of periapical granulomas in primary teeth." (PMID 30012121, 2018). "Our results showed that IL-1α and IL-1β were both expressed in periapical granulomas and radicular cysts." (PMID 30012121, 2018). "A significant positive correlation was observed between the protein expression levels of IL-1α and IL-1β and the inflammation grade in periapical granulomas from primary teeth (P < 0.05)." (PMID 30012121, 2018). "In our study, we found that IL-1α and IL-1β levels increased in the moderate and severe inflammatory cell infiltration subgroups of periapical granulomas." (PMID 30012121, 2018). "Expression levels of the cytokines IL-1α and IL-1β in periapical granulomas from primary teeth increased with increasing inflammatory severity and appeared to be a contributing factor to the progression of periapical lesions." (PMID 30012121, 2018). "Our immunohistochemistry results showed that positive IL-1α and IL-1β staining was found not only in the inflammatory cells but also in the epithelial cells and on the vascular endothelium in both periapical granulomas and radicular cysts from primary teeth." (PMID 30012121, 2018). "In summary, the pro-inflammatory cytokines IL-1α and IL-1β are expressed in both periapical granulomas and radicular cysts in primary teeth." (PMID 30012121, 2018). "Furthermore, expression levels of the cytokines IL-1α and IL-1β in periapical granulomas in primary teeth increased with increasing inflammatory severity and appeared to be a contributing factor to periapical lesion progression." (PMID 30012121, 2018). "Moreover, a significant positive correlation was observed between the protein expression levels of IL-1α and IL-1β in periapical granulomas from primary teeth (P < 0.01)." (PMID 30012121, 2018). "Particularly, our data from periapical granulomas from primary teeth showed a positive correlation between IL-1α and IL-1β expression levels and the inflammation grade, suggesting that increased IL-1α and IL-1β expression occurred parallel to the severity of the inflammation." (PMID 30012121, 2018). "In addition, the cytokines IL-1α and IL-1β are abundantly expressed in periapical granulomas, and these high levels of IL-1α and IL-1β expression are consistent with the inflammation severity." (PMID 30012121, 2018).
periodic fever syndrome (1 paper, 2012). Fevers of unknown etiology recurring over months or years. "Similarly, IL-1β, but not IL-1α, is the etiologic agent of hereditary periodic fever syndromes and other “autoinflammatory” diseases in humans." (PMID 23056330, 2012).
Pneumovirus Infections (1 paper, 2023). Infections with viruses of the genus PNEUMOVIRUS, family PARAMYXOVIRIDAE. "The IL-1α gene expression was reported to be upregulated in the lungs of Nrf2−/− mice 30 min after lipopolysaccharide (LPS) challenge, and there was no change in a model of pneumovirus infection." (PMID 37022178, 2023).
polyarthritis (1 paper, 2019). "Mice overexpressing human IL-1α Tg present chronic destructive polyarthritis, characterized by hyperplasia of the synovial lining, pannus formation and cartilage destruction." (PMID 30837986, 2019).
polyp (1 paper, 2023). A usually exophytic mass attached to the underlying tissue by a broad base or a thin stalk. "To further characterize the regulation of IL-1α in polyp epithelial cells in CRSwNP patients, we next examined the expression in cultured NECs in vitro." (PMID 36168003, 2023). "IL-1α in polyp tissues was mainly located in epithelial cells and neutrophils." (PMID 36168003, 2023).
Postpericardiotomy Syndrome (1 paper, 2020). A nonspecific hypersensitivity reaction caused by TRAUMA to the PERICARDIUM, often following PERICARDIOTOMY. "This 6-month study investigated the therapeutic potential of rilonacept, a once-weekly subcutaneously injected IL-1α and IL-1β cytokine trap in patients with both idiopathic and postpericardiotomy syndrome RP and in both acutely symptomatic as well as steroid-dependent clinical presentations." (PMID 33229362, 2020).
prurigo (1 paper, 2020). A name applied to several itchy skin eruptions of unknown cause. "The histological examination of prurigo samples presented an accumulation of neuropeptides that upregulated the production of many proinflammatory cytokines (interleukin (IL)-1α, IL-1β, and IL-8)." (PMID 33182351, 2020).
psoriasis vulgaris (1 paper, 2023). Plaque psoriasis is the most common presentation of psoriasis. "In this observational study using transdermal analysis patch (TAP), levels of skin surface IL-1α, hBD-1, hBD-2, CXCL-1/2, and CXCL-8 of psoriasis vulgaris (PV) patients over biological therapy were assessed." (PMID 38003437, 2023).